ABCB10 (ATP binding cassette subfamily B member 10)
Diseases named in the same sentence as ABCB10 in open-access papers (continued):
Sharing a sentence is not in itself a finding about the gene and the disease.
Insulin resistance (2 papers, 2022 to 2024). Increased resistance towards insulin, that is, diminished effectiveness of insulin in reducing blood glucose levels. "In addition to potentially causing fasting hyperinsulinemia to initiate insulin resistance, increased beta-cell ABCB10 expression in humans could elevate T2D risk by limiting GSIS capacity as well." (PMID 34823065, 2022). "As a result, the excessive increase in bilirubin production mediated by ABCB10 in high-fat diet fed mice altered hepatocellular metabolism and redox to favor steatosis and insulin resistance." (PMID 38290384, 2024). "Accordingly, hepatocyte-specific deletion of ABCB10 protected from high-fat diet induced hepatic steatosis and insulin resistance, by increasing mitochondrial respiration and restoring ROS-dependent insulin signaling." (PMID 38290384, 2024). "Constitutive deletion of Abcb10 in beta-cells protected mice from hyperinsulinemia and insulin resistance by limiting HFD-induced beta-cell expansion." (PMID 34823065, 2022). "Beta-cell ABCB10 is required for HFD to induce insulin resistance in mice by amplifying beta-cell mass expansion to maladaptive levels that cause fasting hyperinsulinemia." (PMID 34823065, 2022). "•ABCB10 deletion in mouse beta-cells protects from HFD-induced insulin resistance." (PMID 34823065, 2022). "This speculation stems from our mouse data showing that beta-cell-specific ABCB10 deletion in mice limits HFD-induced beta-cell mass expansion, while protecting against fasting hyperinsulinemia and insulin resistance." (PMID 34823065, 2022).
acute liver failure (1 paper, 2024). Rapid deterioration of liver function causing encephalopathy and coagulopathy. "Consequently, ABCB10 gain-of-function in human hepatocytes could potentially decrease acute liver failure by decreasing the inflammatory flare caused by excessive neutrophil activity." (PMID 38290384, 2024).
alcoholic hepatitis (1 paper, 2024). Acute hepatitis resulting from ingestion of alcohol. "We show that ABCB10 gain-of-function in liver is sufficient to mitigate neutrophilic inflammation and markers of NET formation in mice with alcoholic hepatitis (AH), with ABCB10 protein content being markedly decreased in humans with AH." (PMID 38290384, 2024). "•Liver ABCB10 content is decreased in humans and mice with alcoholic hepatitis (AH)." (PMID 38290384, 2024).
alcoholic liver diseases (1 paper, 2024). A disorder caused by damage to the liver parenchyma due to alcohol consumption. "To determine the role of ABCB10 in alcoholic liver disease, we first measured the effects of ASH and AH on ABCB10 protein content in total liver lysates." (PMID 38290384, 2024). "However, the role of hepatic ABCB10 and its redox actions on alcoholic liver disease are completely unknown." (PMID 38290384, 2024). "However, the role of ABCB10 redox actions on alcoholic liver disease is unknown." (PMID 38290384, 2024). "Altogether, these data indicate that ABCB10 downregulation can be playing a specific role in the development of AH, but not in earlier and milder stages of alcoholic liver disease." (PMID 38290384, 2024).
Anxiety (1 paper, 2012). Intense feelings of nervousness, tension, or panic often arise in response to interpersonal stresses. "Furthermore, assessment of activity, exploratory behavior, and anxiety levels revealed behavioral alterations in ABCB10/0 and ABCC10/0 mice, whereas ABCG20/0 mice were mostly unaffected." (PMID 22545122, 2012).
cardiomyopathy (1 paper, 2024). A disease of the heart muscle or myocardium proper. "In this study, a similar phenotype was observed in Abcb10 cKO hearts as in p32 cKO hearts, suggesting that a similar mechanism caused cardiomyopathy, induced lysosomal dysfunction and subsequent death." (PMID 38655715, 2024).
chronic heart failure (1 paper, 2024). "We propose that Abcb10 cKO mice develop cardiac ferroptosis associated with lysosomal dysfunction as a model of chronic heart failure." (PMID 38655715, 2024). "Our findings suggest that Abcb10 is required for the maintenance of cardiac function and reveal a novel pathophysiology of chronic heart failure related to lysosomal function and ferroptosis." (PMID 38655715, 2024). "To examine the potential role of Abcb10 in chronic heart failure, we generated a cardiac myocyte-specific Abcb10 knockout mouse." (PMID 38655715, 2024).
colon carcinoma (1 paper, 2015). "The role of ABCA4 in cancer is largely unknown to date, whereas ABCB10 was previously shown to be expressed in drug-resistant HT-29 colon carcinoma cells." (PMID 25889687, 2015).
epidermoid carcinoma (1 paper, 2025). "ABCB10 contributes to cisplatin resistance in epidermoid carcinoma cells." (PMID 40141294, 2025).
erythroleukemia (1 paper, 2023). Acute erythroid leukemia characterised by the presence of at least 50% erythroid precursors and at least 20% myeloblasts in the bone marrow. "Loss of Abcb10 resulted in an inability to hemoglobinize upon differentiation in both K562 and mouse murine erythroleukemia cells with reduced heme and intermediate porphyrins and decreased levels of aminolevulinic acid synthase 2 activity." (PMID 37269954, 2023). "In this study, we generated Abcb10 deletion cell lines in both mouse murine erythroleukemia and human erythroid precursor human myelogenous leukemia (K562) cells to better understand the consequences of Abcb10 loss." (PMID 37269954, 2023). "The phosphorylation of eIF2S1 limits translation and cell proliferation, and the proliferation defects seen in both Abcb10-null K562 and MEL erythroleukemia cell lines could be recovered by increasing arginine levels in growth media." (PMID 37269954, 2023).
esophageal cancer (1 paper, 2022). A primary or metastatic malignant neoplasm involving the esophagus. "With the progress of circRNA research, relevant studies demonstrated that Circ-ABCB10 is abnormally expressed in various cancers, such as esophageal squamous cell carcinoma and esophageal cancer." (PMID 35646916, 2022).
heart failure (1 paper, 2024). Inability of the heart to pump blood at an adequate rate to meet tissue metabolic requirements. "The Abcb10 knockouts exhibited progressive worsening of cardiac fibrosis, increased cardiovascular risk markers and mitochondrial structural abnormalities, suggesting that the pathology of heart failure is related to mitochondrial dysfunction." (PMID 38655715, 2024). "Examination of these mice revealed that Abcb10 KO induced heart failure and mitochondrial dysfunction, as well as lysosomal dysfunction leading to ferroptosis." (PMID 38655715, 2024).
Hepatic steatosis (1 paper, 2024). Steatosis is a term used to denote lipid accumulation within hepatocytes. "We previously published that deletion of hepatic ABCB10 in male mice with NAFLD increased mitochondrial respiration and protected from hepatic steatosis." (PMID 38290384, 2024). "We did not observe that ABCB10 loss worsened liver neutrophil inflammation or metabolism in ASH, as no upregulation in liver MPO content, no decreases in mitochondrial fat oxidation capacity and no exacerbation of hepatic steatosis were observed in ABCB10 L-KO mice under the NIAAA model." (PMID 38290384, 2024).
Hyperglycemia (1 paper, 2022). An increased concentration of glucose in the blood. "In all, our study demonstrates that ABCB10 in beta cells is a key determinant of the response of an organism to high caloric diets, playing a maladaptive role that promotes hyperglycemia by limiting GSIS and increasing fasting insulinemia." (PMID 34823065, 2022). "This latter data was reveals that the improvement in beta-cell function in Abcb10 +/- mice can contribute to combating HFD-induced hyperglycemia even when the Abcb10 genetic dosage is halved in all tissues." (PMID 34823065, 2022). "In other words, all the beta-cell phenotypes observed are not exclusively explained by the absence of beta-cell autonomous ABCB10 actions but by the long-term consequences of preventing severe hyperglycemia." (PMID 34823065, 2022).
ischemia (1 paper, 2026). A hypoperfusion of the BLOOD through an organ or tissue caused by a PATHOLOGIC CONSTRICTION or obstruction of its BLOOD VESSELS, or an absence of BLOOD CIRCULATION. "Differences between our data in skeletal muscle and previous findings in cardiac muscle emerge when ABCB10+/− mice are subjected to cardiac stress, with diastolic pressures increased and systolic pressures decreased in response to ischemia–reperfusion." (PMID 41545030, 2026).
liver disease (1 paper, 2024). "Thus, our study informs that restoring ABCB10 function in human livers might be a novel strategy to mitigate NET formation and liver inflammation in AH, which are associated with poor prognosis of liver disease." (PMID 38290384, 2024).
lymph-node metastasis (1 paper, 2021). "Furthermore, circ-ABCB10 expression was associated with tumor size, lymph node metastasis, and the International Federation of Gynecology and Obstetrics (FIGO) stage in CC." (PMID 34493213, 2021). "Moreover, higher production level of circ-ABCB10 was close related to lymph-node metastasis, Federation of Gynecology and Obstetrics (FIGO) stage, and tumor size in CC patients." (PMID 34493213, 2021). "Moreover, higher production level of circ-ABCB10 was close related to lymph-node metastasis, FIGO stage, and tumor size in CC patients." (PMID 34493213, 2021).
Obesity (1 paper, 2022). Accumulation of substantial excess body fat. "In the pathological context of T2D in humans, ABCB10 variant rs348330 (G/A) has been consistently associated with a higher risk to develop T2D (p-value 3.37e-21, OR of 0.957), with this significant association to T2D being preserved after adjusting for obesity (BMI) (p-value 2.709e-8, OR of 0.9484)." (PMID 34823065, 2022). "The improvement in glucose tolerance induced by halving beta-cell ABCB10 expression was not explained by protection from obesity, as βHET mice had no changes in body weight." (PMID 34823065, 2022).
oral squamous cell carcinoma (1 paper, 2022). "In oral squamous cell carcinoma, circ-ABCB10 was found to be upregulated and related to metastasis and tumor clinical staging of oral squamous cell carcinoma (OSCC) patients, aggravating the progression of OSCC by sponging miR-145-5p." (PMID 35646916, 2022).
pancreatic cancer (1 paper, 2025). "There are no data on role of ABCB10 in antitumor drug response of pancreatic cancer." (PMID 40141294, 2025).
prostate tumor (1 paper, 2021). "Using one probe, XLB, here we identified ATP-binding cassette (ABC) transporters ABCA3, ABCB4, and ABCB10 as unfractionated microsomal GlcCer-binding proteins in DU-145 prostate tumor cells." (PMID 34597626, 2021).
rectal cancer (1 paper, 2022). A primary or metastatic malignant neoplasm that affects the rectum. "The interesting thing is that in rectal cancer, the number of circ-ABCB10 is decreasing but has an effect of inhibiting ferroptosis and apoptosis by regulating miR-326/CCL5." (PMID 35646916, 2022).
steatosis (1 paper, 2024). Increased lipid within the cytoplasm of cells. "Accordingly, ABCB10 gain-of-function selectively increased the mitochondrial GSH/GSSG ratio and decreased hepatic 4-HNE protein adducts, without elevating mitochondrial fat expenditure capacity, nor mitigating steatosis and hepatocyte death." (PMID 38290384, 2024).
urinary bladder cancer (1 paper, 2023). A primary or metastatic malignant neoplasm involving the bladder. "The roles of ABCC5, ABCA8, ABCC10, ABCB10, ABCG1, ATP7B, ABCG2, and mitochondrial SLC25A10 in platinum-receiving urinary bladder cancer patients should be the subject of further investigation." (PMID 36650399, 2023).
tumor (10 papers, 2012 to 2026). "In vivo experiments further revealed that circ-ABCB10 depletion caused the notable reduction of tumor volume and weight in CC xenograft tumors." (PMID 34493213, 2021). "Circ-ABCB10 loss suppresses cell proliferation/migration and hampers xenograft tumor growth in non-small cell lung cancer." (PMID 34493213, 2021). "ABCG2 was correlated with tumor progression, prognosis and drug resistance, and ABCB10 was associated with tumor progression as well as prognosis." (PMID 33825659, 2021). "Additionally, the abnormal expression of circ-ABCB10 and miR-128-3p in CC tumor tissues and cell lines indicates the potential diagnostic value of circ-ABCB10 and miR-128-3p in CC." (PMID 34493213, 2021). "Moreover, miR-128-3p expression was demonstrated to be conspicuously reduced in CC tumor tissues (n = 34) than that in adjacent normal tissues (n = 34), and to be reversely associated with circ-ABCB10 expression in CC tissues." (PMID 34493213, 2021). "In this case, it can easily be supposed that circ-ABCB10 can regulate the expression of multiple downstream genes, which has a synergistic effect on tumor growth." (PMID 35646916, 2022). "It has been reported that circ-ABCB10 participates in tumor proliferation and migration by sponging several miRNAs via various transmitting pathways." (PMID 35646916, 2022). "This illustrates that the level of circ-ABCB10 can also have an influence on the proliferation and invasion of tumor." (PMID 35646916, 2022). "Generally speaking, these studies indicate that the expression of Circ-ABCB10 is dynamically regulated in tumor progression." (PMID 35646916, 2022). "Circ-ABCB10 expression was markedly up-regulated in CC tumor tissues (n = 34) versus adjacent normal tissues (n = 34)." (PMID 34493213, 2021). "Similar to proliferation and invasion, circ-ABCB10 also has an adverse effect on tumor metastasis." (PMID 35646916, 2022). "Furthermore, the OS was worse in ccRCC patients with high tumor tissue circ-ABCB10 expression compared with ccRCC patients with low expression of circ-ABCB10 in tumor tissue." (PMID 35223991, 2022). "In addition, circ-ABCB10 can also promote the function of Bmi-1 by sponging miR-203 and enhance the tumor growth in osteosarcoma." (PMID 35646916, 2022). "Some studies have demonstrated that circ-ABCB10 could stimulate tumor growth and insulin resistance (IR)." (PMID 35646916, 2022). "Furthermore, the high expression of circ-ABCB10 was closely related to the pathological grade and tumor lymph node metastasis stage." (PMID 35646916, 2022). "It indicates that there may be a correlation between circ-ABCB10 and miR-203 in the proliferation of tumor." (PMID 35646916, 2022). "Xenograft tumor assays confirmed that circ-ABCB10 knockdown inhibited CC tumor growth." (PMID 34493213, 2021). "Thus, we can speculate that circ-ABCB10 may sponge different miRNAs to regulate the same tumor growth." (PMID 35646916, 2022). "Future work is needed to determine the efficacy of targeting ABCB10 or its downstream pathway in a combined DOX and tumour model." (PMID 41545030, 2026). "Over 9 years during which the patient received multiple lines of therapy, the tumor maintained BRCA1 LOH, copy number gains in ABCB10/11, high aneuploidy scores (≥13), MYC amplifications (CN ≥ 10) and PARP1 gains (CN = 4)." (PMID 36344544, 2022). "Considering the tumor heterogeneity of the two clusters, we identified six prognostic genes (PIM2, PET117, SMARCA5, TAF9, ABCB10, MKP1) among the m6A-hypoxia genes and developed a scoring system to evaluate m6A modification patterns and hypoxia status." (PMID 36105819, 2022).
cancer (9 papers, 2015 to 2025). A tumor composed of atypical neoplastic, often pleomorphic cells that invade other tissues. "For example, hsa_circ_0011290, hsa_circ_0000190, and circ-ABCB10 regulated proliferation, apoptosis, and migration of cancer cells through mode-of-action of sponging miR-1252-5p." (PMID 36694627, 2023). "Circ-ABCB10, a circular RNA originating from exons of ABCB10 located on chromosome 1q42, has been proven to play an important role in different types of cancers." (PMID 35646916, 2022). "In this article, we discussed and reviewed the role of circ-ABCB10 in different cancers and comprehensively summarized a list of related signaling pathways in various tumors." (PMID 35646916, 2022). "Metastasis is an important step in cancer progression, and circ-ABCB10 can influence cancer metastasis in different ways." (PMID 35646916, 2022). "Several studies also demonstrated that circ-ABCB10 can sponge miRNAs to regulate certain oncogenes in cancers including NSCLC." (PMID 31931771, 2020). "Due to these unique characteristics, circ-ABCB10 is related to several characteristics of cancers." (PMID 35646916, 2022). "Thus, it is significant to summarize the function of Circ-ABCB10 in the occurrence and progression of human cancers." (PMID 35646916, 2022). "From this perspective, circ-ABCB10 might be a potential biomarker for the diagnosis and prognosis of human cancers." (PMID 35646916, 2022). "Here, we report the primary findings of recent research studies by many contributors about the roles of circ-ABCB10 in cancer and clearly formulate its influence and functions in different aspects of cancer biology, which gives us a broad picture of circ-ABCB10." (PMID 35646916, 2022). "However, the knowledge on the roles of circ-ABCB10 in cancer is still limited, and there are still many unresolved problems." (PMID 35646916, 2022). "It is demonstrated that circ-ABCB10 has a positive role in cancer metastasis." (PMID 35646916, 2022). "Expression and functions of circ-ABCB10 in different cancers." (PMID 35646916, 2022). "This was the first time for circ-ABCB10 to be related to drug sensitivity in cancer cells." (PMID 31931771, 2020).
bacterial infections (1 paper, 2024). "Consequently, it is expected that restoring the endogenous ABCB10 protein lost in AH will only prevent neutrophil hyperactivation specifically caused by AH, and will not suppress the capacity to form the physiological NETs needed to fight bacterial infections." (PMID 38290384, 2024).
mitochondrial disease (1 paper, 2024). "Here, Abcb10 knockout in the heart resulted in impaired mitochondrial function, indicated by progressively elevated expression of mitochondrial disease markers." (PMID 38655715, 2024). "In the Abcb10 cKO mice, the gene expression of the mitochondrial disease biomarkers Gdf15 (growth differentiated factor 15) and Fgf21(fibroblast growth factor 21) gradually increased with age, suggesting that mitochondrial dysfunction became progressively more severe as these mice aged." (PMID 38655715, 2024).
ABCB10 also shares sentences with these, for which no sentence is quoted: epithelial ovarian cancer (2 papers); non-small cell lung carcinoma (2); alcoholic steatohepatitis (1); clear cell renal cell carcinoma (1); dilated cardiomyopathy (1); esophageal squamous cell carcinoma (1); Hyperinsulinemia (1); iron deficiency (1); laryngeal carcinoma (1); laryngeal squamous cell carcinoma (1); liver cancer (1); myelogenous leukemia (1); ovarian cancer (1).